USP28 (ubiquitin specific peptidase 28)
Diseases named in the same sentence as USP28 in open-access papers (continued):
Sharing a sentence is not in itself a finding about the gene and the disease.
lung carcinoma (17 papers, 2015 to 2024). "To investigate the mutational as well as the expression status of USP28 in lung cancer, we analysed publicly available datasets of human tumours (and EV1A)." (PMID 32128997, 2020). "The bioinformatic analyses also showed abnormal levels of TIAM1 and USP28 genes in the lung cancer tissues in the present study." (PMID 38711144, 2024). "USP28 was found to be upregulated already at an early stage in lung cancer, when compared to wild‐type tissue." (PMID 35364627, 2022). "The development of lung cancer is related to decreased miR-3940-5p accumulation in cancer cells via targeting ubiquitin-specific peptidase 28 and cyclin D1 to suppress cancer progression." (PMID 35235752, 2022). "Analysing public data sets revealed that gene expression of the PI3K‐MAPK downstream effectors, AKT2 and BRAF, positively correlated with USP28 in lung cancer cell lines and in various tumour entities." (PMID 35364627, 2022). "In contrast, miR-3940-5p suppresses lung cancer progression by downregulating multiple oncogenes, such as ubiquitin-specific peptidase-28 and cyclin D1." (PMID 35235752, 2022). "All data together indicated that the downregulation of c-Myc, HK2, PKM2, LDHA, PHGDH, PSAT1, cyclin D1, and CDK6 in lung cancer cells was related to the ubiquitin-protein degradation pathway, which was the result that the USP28 was inhibited by SGH." (PMID 33572615, 2021). "Hypoxia, as well as treatment with Ni compounds, contributed to the transcriptional repression of USP28 in A549 lung cancer cells via increased dimethylation of histone H3 lysine 9 at the USP28 promoter." (PMID 31208103, 2019). "Furthermore, a recent investigation showed a reduction in c-Myc, Cyclin D1 and CDK6 in si-USP28-treated lung cancer cell lines." (PMID 36879346, 2023). "In addition to SGH, AZ1 is another inhibitor of USP28 that is quite significant for the treatment of lung cancer." (PMID 36879346, 2023). "Finally, Kaplan–Meier analysis of human lung cancer patient data revealed that both USP28 and SREBF2 were indicative of poor survival in a mixed cohort." (PMID 37202505, 2023). "Furthermore, expression of HMGCS1 and FDFT1 was also reduced in lysates from KPLU compared to KPL tumours, providing additional evidence that Usp28 regulates Srebp2 in lung cancer." (PMID 37202505, 2023). "Stabilization of these onco-proteins during CPPD exposure indeed depends on USP28, as the lung cancer cell line SK-MES1 (SCC), which is mutant for USP28 and expresses low levels thereof, showed some degree of c-JUN or c-MYC destabilization after CPPD treatment." (PMID 34611298, 2022). "To determine whether the promise of USP28 as a target in mouse lung cancer models can be translated to a human scenario, we established human xenograft tumour models." (PMID 34636321, 2021). "Downregulating USP28 expression can inhibit the proliferation and growth of lung cancer cells." (PMID 33572615, 2021). "miR‐4295 has been shown to directly target USP28, which may function as a tumour suppressor in non‐small cell lung cancer." (PMID 26756701, 2016). "Since both proto‐oncogenes exert an important role during oncogenic transformation and are increased upon EGFR‐PI3K‐MAPK‐mediated oncogenic transformation, we wondered whether the regulation of USP28 in lung cancer depends on these transcription factors as well." (PMID 35364627, 2022). "In colon carcinoma and lung cancer, c-MYC expression is maintained by USP28 and USP37, respectively." (PMID 36985413, 2023). "In this study, we report that the deubiquitylase USP28 presents a UPS enzyme, which is commonly upregulated during early stages of oncogenic transformation in lung cancer." (PMID 35364627, 2022). "Initially, USP28 was reported to play an important role in the DSB response because depletion of USP28 results in the reduction of protein levels of 53BP1, CHK2, MDC1, and NBS1 after ionizing radiation in H460 lung carcinoma cells." (PMID 36436562, 2022).
lung carcinoma (continued). "Usp28 was initially reported to play an important role in DSB response by stabilizing many proteins, including 53BP1, Chk2, Mdc1, and Nbs1, in H460 lung carcinoma cells." (PMID 34473993, 2021). "The expression levels of the USP28 gene in lung cancer tissues were higher compared to the normal tissues." (PMID 38711144, 2024). "In different cancers, cellular turnover of c-MYC has been regulated by different USPs, with notable examples including the maintenance of c-MYC turnover by direct physical interactions of USP28 in colon carcinoma, USP36 in breast carcinoma and USP37 in lung cancer." (PMID 36985413, 2023). "Moreover, USP28, SREBF2 and HMGCS1 were significantly upregulated in LSCC compared to LADC in tissue from a cohort of human lung cancer patients." (PMID 37202505, 2023). "Next, lung cancer PC9 and H157 cells were transfected with siRNA-USP28 (si-USP28)." (PMID 33572615, 2021). "Moreover, a remarkable decrease in USP28 and its substrates, such as c-Myc and Cyclin D1, was shown in lung cancer cells treated with SGH, suggesting that the anticancer function of SGH may be mediated by the downregulation of USP28." (PMID 36879346, 2023). "Finally, combining USP28 targeting with targeted therapy against commonly found oncogenic drivers potentiates treatment responses, at least in cellulo, indicating that the UPS system, exemplified by USP28, is a promising target structure for lung cancer." (PMID 35364627, 2022).
colon carcinoma (13 papers, 2015 to 2024). "Previous studies revealed that USP28 is required for the stability of oncoproteins such as c-MYC in colon cancer 37-39, and c-JUN and NOTCH in colorectal cancer." (PMID 33664871, 2021). "A study showed that SUMOylation at Lys99 residues of USP28 could inhibit the activity of USP28, indicating potential therapeutic role in colon cancer cells and NSCLC cells." (PMID 34177595, 2021). "The therapeutic benefit of USP28 in colon cancer was further demonstrated in another study, where USP28 knockout could increase the life expectancy of animals harboring FBW7-deficient colon tumors." (PMID 29415985, 2018). "Importantly, USP28 is highly expressed in colon cancers, making it a potential pharmacological target to control c-MYC-driving tumor cells." (PMID 29415985, 2018). "c-Myc-dependent tumors (adenocarcinomas and non-small lung, breast, and colon cancer) could potentially respond to USP28, USP36, USP37, all DUBs affecting c-Myc protein turnover." (PMID 27516771, 2016). "Coincidentally, USP28 is homologous to USP25 and is upregulated in colon cancer cells and NSCLC cells." (PMID 34177595, 2021).
glioma (12 papers, 2017 to 2025). A benign or malignant brain and spinal cord tumor that arises from glial cells (astrocytes, oligodendrocytes, ependymal cells). "Moreover, Kaplan‒Meier survival analysis demonstrated that overexpression of USP28 was associated with shorter overall survival in cancers, including non-small cell lung cancer, glioma and hepatocellular carcinoma." (PMID 36879346, 2023). "Experimental validation further supported this conclusion, showing that one of the identified targets, USP28, enhanced glioma cell proliferation." (PMID 41154382, 2025). "The population data and IHC results all indicated that the USP28 were highly expressed and translated in glioma tissues, compared with normal tissues." (PMID 35299740, 2022). "One study revealed that the FBXW7-185aa coded by circ-FBXW7 regulating FBXW7 protein via competitively binding to USP28 in glioma." (PMID 35814468, 2022). "A previous study in glioma implicated that the short protein FBXW7-185aa interacts with the deubiquitinating enzyme USP28, preventing USP28 from binding to FBXW7 and antagonizing USP28-induced c-Myc stabilization." (PMID 33466455, 2021). "The significance of USP28 in glioma tumorigenesis has been demonstrated by its positive regulation on MYC, which is dysregulated in the majority of gliomas and difficult to target directly." (PMID 29415985, 2018). "Ectopic USP28 expression promoted proliferation of SW1783 glioma cells both in vitro and in vivo, and conferred enhanced tumorigenicity in a nude mouse model." (PMID 29415985, 2018). "The USP28 protein level in human glioma tissues was directly correlated with glioma grade, and was inversely correlated with patient survivals." (PMID 29415985, 2018). "Similarly, a higher level of USP28 appeared in high-grade glioma samples compared with glioma tissues with lower pathologic grade." (PMID 36879346, 2023). "In glioma, where several DUBs have been found to contribute to tumor progression by gene expression profiling interactive analysis, a prognostic role for Ubiquitin-Specific Protease 28 (USP28) was proposed." (PMID 36578788, 2022). "An illustrative example is the role of circFBXW7 in inhibiting the development of glioma tumors through the production of FBXW7-185 aa, this reduces c-Myc stabilization by opposing the USP28-mediated stabilization process." (PMID 39440063, 2024). "Importantly, USP28 promoted MYC expression, which was required for USP28-induced cell growth in human glioma." (PMID 29415985, 2018). "In addition to the higher expression of USP28 discovered in a variety of cancers, including glioma and non-small cell lung cancer, a negative correlation between the level of USP28 and the prognosis of these cancers has been demonstrated." (PMID 36879346, 2023). "It was determined that USP28 was upregulated in human gliomas but not in normal brain tissues." (PMID 29415985, 2018).
non-small cell lung carcinoma (12 papers, 2015 to 2025). A group of at least three distinct histological types of lung cancer, including non-small cell squamous cell carcinoma, adenocarcinoma, and large cell carcinoma. "The deubiquitinating enzyme USP28 mediates STAT3 signaling in non-small-cell lung cancer cells, and USP28 interacts with STAT3 and enhances its stability by inducing the deubiquitination of STAT3." (PMID 39773987, 2025). "In non-small-cell lung cancer, USP28 appears to mediate STAT3 signaling through deubiquitination and stabilization." (PMID 39076972, 2024). "miR-3940-5p suppresses the proliferation of non-small cell lung cancer cells by targeting cyclin D1 and ubiquitin specific peptidase-28." (PMID 38501059, 2024). "The expression level of USP28 was relevant to the poor prognosis of some cancers, including colon cancer, bladder cancer, and non-small-cell lung cancer (NSCLC)." (PMID 37450415, 2023). "Further, the high expression of the deubiquitinating enzyme USP28 was targeted by miR-4295, promoting non-small cell lung cancer cell proliferation." (PMID 37450415, 2023). "Interestingly, USP28 promoted tumor growth including non-small cell lung cancer and colorectal cancer." (PMID 29707125, 2018). "Apart from miR-500a-5p, miR-3940-5p, which has been demonstrated to be decreased in non-small cell lung cancer, has the capacity to connect with the 3’-UTR of USP28 and then lead to the degradation and repression of USP28." (PMID 36879346, 2023). "For instance, loss of USP28 in nude mice resulted in delayed tumor growth of non-small cell lung cancer, which was mediated by the attenuation of STAT3 (a molecule that can be deubiquitinated by USP28) signaling." (PMID 36879346, 2023). "Similar to the results in nude mice, suppression of cell growth occurred in human non-small cell lung cancer cell lines lacking USP28 as well." (PMID 36879346, 2023). "Moreover, the USP28 substrate STAT3 participates in the drug resistance of cancer therapy, suggesting that USP28 may play an essential role in therapy resistance in non-small cell lung cancer." (PMID 36879346, 2023). "Additionally, USP28-mediated FOXK1 deubiquitination activates the Hippo signaling pathway to regulate cell proliferation and radiosensitivity, while targeting USP47 enhances the efficacy of KRAS G12C inhibitors in mutant non-small cell lung cancer through regulation of c-Myc deubiquitination." (PMID 41488674, 2025).
bladder cancer (8 papers, 2016 to 2025). "ATG7 overexpression stabilizes CD44 by upregulating USP28 protein, which in turn modulates stem cell-like properties, invasion and human lung metastasis in bladder cancer." (PMID 40707430, 2025). "Following the upregulation of USP28 induced by ATG7, CD44 can be deubiquitinated and stabilized by USP28, which mediates the enhancement of the cancer stem cell-like properties of bladder cancer." (PMID 36879346, 2023). "It was reported that the deubiquitylation of CD44s protein by USP28 is required for maintaining the invasive and metastatic phenotypes of CSCs in human bladder cancer." (PMID 32168951, 2020). "A recent publication has proposed USP28 to be a potential predictive marker in bladder cancer, as they found correlation of USP28 with tumor histological grade, clinical stage, recurrence, and survival." (PMID 27014628, 2016). "The clinical significance of USP28 was also demonstrated in human bladder cancer." (PMID 29415985, 2018). "Additionally, iorhapontigenin (ISO) is isolated from the Chinese herb Gnetum cleistostachyum, and a reduction in the activation of the USP28 mRNA 3’-UTR appeared in bladder cancer cells treated with ISO, through which the suppression of bladder cancer was promoted." (PMID 36879346, 2023). "A study showed that bladder cancer cells treated with a CD44 inhibitor had a tendency to reduce the sizes and numbers of tumorospheres, indicating that USP28 can play a vital role in tumor progression by mediating CD44." (PMID 36879346, 2023). "-The TET1/USP28/CD44/RhoGDIβ pathway was identified as the regulator of the oncogenic activities of ATG7 for stem-like property, invasion, and lung metastasis of human bladder cancer cells." (PMID 35269796, 2022). "Binding of USP28 to CD44 standard (CD44s) protein leads to removal of the ubiquitin group from the ubiquitinated CD44s protein, resulting in the stabilization of CD44s protein to mediate the stem-like property of human bladder cancer cells." (PMID 35269796, 2022). "It has been determined that USP28 was overexpressed in bladder cancers compared to adjacent non-cancerous tissues at both the mRNA and protein levels." (PMID 29415985, 2018).
melanoma (8 papers, 2018 to 2023). A malignant, usually aggressive tumor composed of atypical, neoplastic melanocytes. "Surprisingly, BRAFV600E‐transformed BEAS‐2B demonstrated a high degree of sensitivity towards AZ1, as it was previously reported that, in melanoma, loss of USP28 was required to induce oncogenic transformation and resistance." (PMID 35364627, 2022). "An adaptive response that is lost in melanoma patients harboring mutations in USP28 resulting in BRAF stabilization, hyperactivation of the MAPK signaling, and resistance to therapies targeting this pathway." (PMID 29880484, 2018). "Collectively these results indicate that USP28 is frequently mutated in melanoma and that low expression levels of USP28 correlate with poor overall survival." (PMID 29880484, 2018). "FBW7 and USP28 mutations have recently been identified in melanoma." (PMID 31416288, 2019). "Importantly, we demonstrate that USP28 expression is deleted in ∼10% of all melanoma patients, of which half of these patient’s harbor mutations in BRAF (V600E), NF1, or NRAS, supporting a role for USP28 loss in melanoma progression." (PMID 29880484, 2018). "As hyperactivation of the MAPK pathway has previously been demonstrated to enhance resistance to MAPK pathway inhibitors, we speculated that loss of USP28 in BRAF (V600E) melanoma cell lines would limit sensitivity of these cells lines to the BRAF inhibitor vemurafenib." (PMID 29880484, 2018). "As USP28 is frequently deleted in a proportion of melanoma patients, the authors suggested rigosertib as a potential therapeutic strategy for USP28-depleted cells, demonstrating an increased sensitivity of USP28-depleted cells to rigosertib." (PMID 37111716, 2023). "Of clinical relevance, decreased USP28 expression is more frequently observed in BRAFV600E melanoma patients and leads to a poorer overall survival, indicating the possible role of USP28 as a relevant factor in melanoma progression." (PMID 35884430, 2022). "Cross-correlation of USP28 expression in BRAF (V600E) melanoma patients indicated that in this subset of patients, once again low levels of USP28 conferred lower overall survival." (PMID 29880484, 2018). "In line with previous results, depletion of USP28 in all the melanoma cell lines tested resulted in increased stabilization of BRAF and enhanced downstream MAPK activation." (PMID 29880484, 2018). "We decided to focus our attention on USP28, as USP28 forms a complex with FBW7, a protein recently described to be mutated in melanoma." (PMID 29880484, 2018). "USP28 expression was significantly down-regulated in 32% (38/118) of melanoma patients with 10% (11/118) of melanoma patients appearing to have only minimal USP28 expression." (PMID 29880484, 2018). "To corroborate the sensitivity of USP28-depleted melanoma cells to rigosertib, we analyzed cell viability in a dose-dependent manner." (PMID 29880484, 2018). "As anticipated, USP28-depleted melanoma cell lines were more resistant to BRAF inhibitor treatment and then their wild-type counterparts, as demonstrated by a rightward shift in the dose–response curve." (PMID 29880484, 2018). "To evaluate the clinical significance of USP28 in melanoma, we probed a publically available melanoma patient cohort (TCGA)." (PMID 29880484, 2018). "To further analyze the expression of USP28 in melanoma, we cross-referenced whole genome sequencing data with copy number variation (CNV) scores from 118 melanoma patients." (PMID 29880484, 2018). "To search for synthetic lethal interactions in melanoma cell lines depleted for USP28, we performed a high throughput synthetic lethal chemical compound screen." (PMID 29880484, 2018). "Similarly, sensitivity to vemurafenib-induced tumor shrinkage can be reduced by depletion of USP28 in immunodeficient mice injected with melanoma cells." (PMID 36879346, 2023).